ZEB1 (zinc finger E-box binding homeobox 1)
Diseases named in the same sentence as ZEB1 in open-access papers (continued):
Sharing a sentence is not in itself a finding about the gene and the disease.
breast carcinoma (continued). "In breast cancer, senile neutrophils produce exosome piR-17,560 in a STAT3-dependent manner, which binds to FTO and increases ZEB1 expression by reducing m6A methylation, promoting chemotherapy resistance and EMT in BC cells." (PMID 38031146, 2023). "Even though ZEB1 was successfully and stably knocked-out in HS578T-Hyg breast cancer cells and M13HS tumor hybrids, the phenotype of the ZEB1-KO cells was only moderately altered as compared to their wildtype counterparts." (PMID 38139138, 2023). "Ectopic expression of ZEB1 enhances VEGFA mRNA expression and promotes angiogenesis, VM formation, and anti-angiogenic therapy resistance in breast cancer, prostate cancer, or colorectal cancer." (PMID 36906615, 2023). "Thus, ZEB1 could be used as a target for treating advanced breast cancer." (PMID 37049543, 2023). "Recent evidence suggests that the interaction between epithelial to mesenchymal transition (EMT) transcription factors like Zinc Finger E-Box Binding Homeobox 1 (ZEB1) and ERα promote breast cancer bone metastasis." (PMID 37915743, 2023). "In two breast cancer studies, the linc-ROR acted as a miR-205 sponge to overexpress ZEB1 and ZEB2 and decrease the expression of E-cadherin." (PMID 36827545, 2023). "In contrast, the HS578T-Hyg breast cancer cells are in a M state due to the expression of “classical” M markers, such as CDH2, VIM, ZEB1 and WNT5A." (PMID 38139138, 2023). "The capacity of CRISPR to induce ZEB1 repression was assessed in two human TNBC cell lines, SUM159 and MDA‐MB‐231, representing models for the claudin‐low mesenchymal subtype of breast cancer." (PMID 37217832, 2023). "One of the Zeb1 interactors is the splicing factor SF3B1, which is overexpressed in breast cancer tissue compared to normal tissue." (PMID 37372954, 2023). "Sanger sequencing revealed one additional nucleotide in the ZEB1 gene of the M13HS-2 ZEB1-KO and -8 ZEB1-KO tumor hybrids, whereas gene editing was much more chaotic in HS578T-Hyg breast cancer cells." (PMID 38139138, 2023). "In breast cancer, YEATS4 recognizes H3K27ac in the ZEB1 promoter and promotes EMT in breast cancer cells." (PMID 37435030, 2023). "In the TCGA dataset, we assessed the expression of key epithelial marker E-cadherin (CDH1) and mesenchymal markers, including vimentin (VIM), MMP9, SNAI2, ZEB1, and ZEB2, about VISTA expression in breast cancer patients using Spearman correlation analysis." (PMID 37152039, 2023). "In comparison to the HS578T-Hyg breast cancer cells, the miRNA-34a-5p levels were about 2-fold lower in the HS578T-Hyg ZEB1-KO cells." (PMID 38139138, 2023). "As a cancer suppressor miRNA, it completely inhibits breast cancer metastasis and chemotherapy resistance by regulating MT (directly targeting EMT activators, such as ZEB1, CDH2, and vimentin)." (PMID 37809692, 2023). "In breast cancer, YEATS4 recognizes histone H3K27ac in the promoter region of ZEB1, thereby promoting ZEB1 expression and accelerating tumor progression." (PMID 37435030, 2023). "Subsequently, upregulated ZEB1 protein binds to the PTEN promoter, inhibiting PTEN expression, activating the AKT pathway, and promoting breast cancer progression." (PMID 37771431, 2023). "The stability of ZEB1 maintained by USP43 and USP51 promotes the proliferation and metastasis of colorectal and breast cancer." (PMID 36906615, 2023). "Downstream targets of ZEB1 and ZEB2 have been well studied in the context of breast cancer and include key genes involved in epithelial plasticity and cellular polarity genes." (PMID 37370762, 2023). "ZNF384 directly transactivates ZEB1 expression and induces an EMT-like phenotype and breast cancer metastasis." (PMID 36100877, 2022).
breast carcinoma (continued). "By contrast, osteosarcoma MG63 and 143B cells, and breast cancer HCC 1395 cells, constitutively expressed both Snail and ZEB1/2." (PMID 35451213, 2022). "Significant downregulation of the miR-200 family, which consists of miR-141, miR-200a, miR-200b, miR-200c, and miR-429, regulates the expressions of mesenchymal markers ZEB1, ZEB2, TWIST1, TWIST2, Snai1, and Snai2 and promotes EMT in breast cancer." (PMID 37533517, 2022). "High levels of EMT markers (ZEB1/ZEB2) and low levels of the miR-200 family (miR-200a/-b/-c) resulted in the resistance of estrogen receptor (ER)-positive breast cancer cells to tamoxifen." (PMID 35682560, 2022). "Recently, ZNF281 was shown to activate epithelial to mesenchymal transition (EMT) transcription factors, ZEB1 and SNAI1 via activation of the TGF-β pathway, promoting EMT and metastasis in breast cancer." (PMID 36207293, 2022). "In breast cancer cells, ZNF384 directly transactivated ZEB1 expression by binding to the activation of the promotor." (PMID 36100877, 2022). "ZEB1/2 are positively correlated with EMT phenotypes, whereas Snail is not positively correlated with the mesenchymal phenotypes of breast cancer and OSCC cells." (PMID 35451213, 2022). "GPNMB-positive cells in breast cancer also show an increased expression of EMT-related genes such as SNAIL, SLUG, and ZEB1, consistent with the fact that GPNMB-positive cells in HNSCC have shown increased invasiveness and migration." (PMID 36061142, 2022). "Among these, ZEB1/2 correlate positively with EMT phenotypes and the aggressiveness of breast cancer and HNSCC cells." (PMID 36140527, 2022). "It has been reported that miR-145 interacts with the transcription factor Oct4 and mediates β-catenin overexpression of the transcription factors Snail and ZEB1/2, thus affecting the EMT process of breast cancer cells." (PMID 35805066, 2022). "With respect to tumor metastasis, the core catalytic subunit BRG1 was found to directly interact with ZEB1, which was required for the induction of EMT in MCF7 breast cancer cells." (PMID 35945219, 2022). "Herein, the probed tumorigenic role of ZNF384 in breast cancer expands the current EMT network, including ZEB1." (PMID 36100877, 2022). "After transfection, we checked their ubiquitination level and found that CSN5 mainly mediates ubiquitination of ZEB1 at K1108, and thus regulates EMT in breast cancer." (PMID 35342335, 2022). "It has been elucidated that increased ZEB1 activity influenced by hyaluronic acid through the ZEB1/epithelial splicing regulatory protein 1/CD44 axis promotes EMT and tumor invasion in breast cancer." (PMID 36402997, 2022). "Hypoxia-induced lncRNA RP11-390F4.3, Wnt/β-catenin signaling, and IKK-2/IκBα/NF-κB pathway in breast cancer can regulate multiple EMT regulators such as Snail, Twist1, and ZEB1/2 to promote tumor metastasis." (PMID 35457185, 2022). "The IHC data revealed that the ZEB1 and DNMT1 expression levels were much higher in breast cancer tissues with high CD163 expression." (PMID 36273188, 2022). "Loss of function studies showed a decreased expression profile in breast cancer, inducing EMT and promoting bone metastasis directly targeting ZEB1 transcription factor." (PMID 37533517, 2022). "Overexpression of EMT-TFs like Twist, Snail, Slug, Zinc finger E-box binding homeobox 1 (ZEB1) and Forkhead box C2 (FOXC2) are known to induce drug resistance in breast cancer." (PMID 34502361, 2021). "In breast cancer, it was revealed that another lncRNA NNT-AS1, functions as ceRNA specific for miR-142-3p, thereby restoring Zeb1 and blocking EMT96." (PMID 33414456, 2021). "We examined changes in the expression levels of the EMT-related proteins ZEB1, SNAI1, SLUG, Twist and E-cadherin after AKR1B10-gene intervention in the breast cancer cells by western blot." (PMID 34419144, 2021).
breast carcinoma (continued). "In breast cancer, NEAT is positively correlated with poor survival rate of patients and contributes to paclitaxel resistance in ovarian cancer cells through miR-194/ZEB1 axis." (PMID 33645623, 2021). "Integrin a6 involvement in radioresistance mechanisms has been previously ascribed to its control over the AKT/ERK pathway and ZEB1/ERK transcription factor, in breast cancer and GBM, respectively." (PMID 34205341, 2021). "For example, the overexpression of miR-21 in MCF7 cells will promote growth and invasion ability of cells; miR-200 family can target ZEB1 and ZEB2 genes to inhibit breast cancer cells." (PMID 33428601, 2021). "In summary, we have identified several potential interactors of Zeb1 EMT-TF, which can serve as targets for attenuation of breast cancer metastasis." (PMID 34074001, 2021). "Metformin leads to reduction in SNAIL, TWIST, and ZEB1 levels, and curcumin inhibits EMT by downregulation of NF‐κB/SNAIL in breast cancer and reactivation of epithelial miRNAs." (PMID 34459003, 2021). "We herein provide further experimental evidence that B3GATL5 regulates EMT and cell proliferation in not only breast cancer cells but also BCSCs via activation of β-catenin and EMT regulator ZEB1." (PMID 33413566, 2021). "In breast cancer cells, SALL4 expression is inversely correlated with that of the EMT marker ZEB1, as well as CDH1." (PMID 34441397, 2021). "The proliferation- and EMT-related proteins including cyclinD1, c-myc, Survivin, Twist, SNAI1, SLUG, ZEB1, E-cadherin, PI3K, p-PI3K, AKT, p-AKT, IKBα, p-IKBα, NF-κB p65, p-NF-κB p65 were detected by western blot in breast cancer cells." (PMID 34419144, 2021). "Wang and colleagues suggested that ZEB1 promoted tumor metastasis through the EMT process in liver and breast cancer." (PMID 34814869, 2021). "In breast cancer, NEAT1 serves as a ceRNA to modulate ZEB1 function by sponging hsa-miR-448, promoting cancer progression." (PMID 35008626, 2021). "Other breast cancer decellularized scaffolds also showed an inverse correlation between EMT and differentiation markers, with an increased expression of VIM, ZEB1 and SNAIL paralleled with a decreased E‐cadherin." (PMID 33368325, 2021). "In breast cancer, GRHL2 down-regulated Smad and ZEB1 expression thus inhibited TGF-β-induced tumor metastasis and ultimately limited the cancer progression." (PMID 33931584, 2021). "MYC increases breast cancer stem cell-like properties and EMT by binding to DOT1L and p300, which stimulates SNAIL, ZEB1, ZEB2 transcription and promotes lysine-79 methylation and H3 acetylation through gene epigenetic modification." (PMID 33390842, 2021). "Intriguingly, during breast cancer development, the accumulation of CIN is apparently prevented, if oncogene activation had taken place in mammary stem cells, engaging a ZEB1‐driven preemptive program with upregulation of the anti‐oxidant MSRB3." (PMID 34459003, 2021). "For instance, HAS2 synthesized hyaluronic acid, enhanced ZEB1 expression and accelerated EMT in breast cancer." (PMID 32862195, 2021). "The conditioned medium derived from ZEB1-overexpressing MDA-MB-231 cells can stimulate osteoclast maturation by upregulating MMP-1 and subsequently promote breast cancer metastasis to bone." (PMID 34109218, 2021). "Further, we demonstrated that co-expression of Zeb1 and CTBP2 in breast cancer patients correlated with the poor survival prognosis, thus signifying the functionality of the Zeb1–CTBP2 interaction." (PMID 34074001, 2021). "In carcinoma or breast cancer, GRHL2 can suppress ZEB1 to block TGF-β-mediated EMT and resistance ability." (PMID 34572451, 2021). "In the very aggressive subgroup of Claudin‐low breast cancer, YAP and ZEB1 interact to drive expression of a common target gene subset to promote EMT and metastasis." (PMID 34459003, 2021).
breast carcinoma (continued). "The mesenchymal MDA-MB-231 breast cancer cell line had lower mRNA expression of epithelial marker CDH1 and higher expression of mesenchymal markers VIM and ZEB1 compared to the MCF-7 and MDA-MB-468 cell lines." (PMID 34207708, 2021). "In breast cancer, ARPC2 expression significantly upregulated the expression of vimentin, N-cadherin, MMP-9, ZEB1, and MMP-3, activated the TGF-β pathway, and eventually led to epithelial–mesenchymal transition (EMT)." (PMID 34307456, 2021). "In mouse mammary carcinoma cells, SNAIL expression is crucial for Zeb1 induction and metastatic dissemination." (PMID 34459003, 2021). "Researchers identified that ZEB1, a core factor of EMT, is amplified in radioresistant subtypes of breast cancer." (PMID 34575114, 2021). "Up-regulated H3K79 methylation on the SNAIL, ZEB1 and ZEB2 promoters enhances EMT-induced breast-cancer invasion and metastasis." (PMID 32042335, 2020). "In fact, MiR-200c regulates EMT by inhibiting ZEB1 and ZEB2 expression in breast cancer cells, while it regulates CSCs heterogeneity via targeting the HIPK1/β-Catenin axis." (PMID 33092068, 2020). "Based on our findings, we proposed that the inhibition of CDK4/6 activity blocks breast cancer EMT and metastasis by decreasing the protein stability of ZEB1." (PMID 32296027, 2020). "Given our observation that USP51 directly binds and deubiquitinates ZEB1, it follows that disrupting the interaction between USP51 and ZEB1 would severely diminish ZEB1 activity and thus the aggressiveness of breast cancer in vitro and in vivo." (PMID 32296027, 2020). "By using MEK1 inhibitor (TAK-733) in combination with radiation therapy for breast cancer cells, significant decrease in migration capacity, including reduction of miR-221 and EMT (ZEB1) marker expression was observed." (PMID 33327491, 2020). "Another TF, LBX1 (Ladybird homeobox 1) can up-regulate the expression of ZEB1/2 and SNAIL1, promoting cell migration and invasiveness in breast cancer." (PMID 32318352, 2020). "For example, in breast cancer cell lines, cells induced to undergo an EMT via introduction of Zeb1 increased the expression of tissue factor, which led to increased coagulant properties." (PMID 32391382, 2020). "In breast cancer, YAP1 can directly interact with ZEB1, (a crucial stimulator of EMT processes) and thereby increases metastatic risk." (PMID 32678516, 2020). "The downregulation of the expression of EMT transcription factors Snail‐1, Snail‐2, Twist‐1, Zeb‐1, and MMP‐3 in IL‐22−/−PyMT tumors suggests that IL‐22 mediates invasion through the EMT pathway in breast cancer." (PMID 31725949, 2020). "EMT is negatively controlled by miR-34 that targets EMT-triggering factors, such as zinc finger E-box binding homeobox 1 (ZEB1) and snail family transcriptional repressor 1 (SNAI1) in breast cancer." (PMID 33066509, 2020). "This activation is induced and maintained by overexpressed ZEB1 recruiting the transcriptional coactivators p300/PCAF to the ATM promoter, which results in the chemoresistance of breast cancer cells." (PMID 32266287, 2020). "In breast cancer cells, NEAT1 reduces the expression of miR-448 to elevate the metastasis and invasion of cancer cells through ZEB1 up-regulation." (PMID 32664703, 2020). "In the present study, we provided evidence that USP51 is a bona fide DUB that targets the ZEB1 protein for deubiquitination and stabilization, which is crucial for the induction of EMT and metastasis in breast cancer." (PMID 32296027, 2020). "In a subset of human breast cancer cell lines and patient samples, the status of USP51 is correlated with ZEB1 expression." (PMID 32296027, 2020). "PGI/AMF induced Epithelial-Mesenchymal Transition (EMT), increasing the expression of ZEB1/ZEB2 (mesenchymal markers; Zinc finger E-Box-binding homeobox 1/Zinc finger E-Box-binding homeobox 2) through the Nuclear Factor-kB (NF-kB) in breast cancer cells." (PMID 31952362, 2020).
breast carcinoma (continued). "In breast cancer cells, HSF2 and the transcription factor zinc finger E-box-binding homeobox 1 (ZEB1) enhance tumorigenesis by cooperatively stimulating the expression of the microRNA cluster miR-183/-96/-182." (PMID 32408596, 2020). "Similar to our findings, a recent report demonstrated the role of SIRT7 in promoting MET in breast cancers through SMAD4 deacetylation mediated suppression of Slug and Zeb1 transcription." (PMID 32656073, 2020). "In the present study, we reported that the inhibition of CDK4/6 significantly reduced breast cancer EMT and metastasis through the induction of ZEB1 protein degradation." (PMID 32296027, 2020). "GRHL2 levels correlated positively with CDH1 (E-cadherin) levels and negatively with ZEB1 in the CCLE dataset and TCGA datasets from breast cancer, ovarian cancer and colorectal cancer." (PMID 32676163, 2020). "Recently, PTBP3 have been demonstrated to promote breast cancer epithelial–mesenchymal transition (EMT), promoting the expression of zinc finger transcription factor ZEB1, an EMT inducer, by binding to ZEB1 3′UTR and preventing its degradation." (PMID 32276354, 2020). "GRHL2 was found to be downregulated specifically in claudin-low subclass breast cancers and to suppress TGF-β-induced, Twist-induced or spontaneous EMT partially by suppressing ZEB1 expression by directly binding to the ZEB1 promoter." (PMID 32014049, 2020). "In breast cancer cells, Cul4A induces an epithelial–mesenchymal transition, and it promotes cancer metastasis by regulating the expression of the EMT regulatory ZEB1 gene." (PMID 31052599, 2019). "Several studies showed that ZEB1 (Zinc Finger E-box Binding Homeobox 1) has an active role in the induction of EMT in diverse epithelial malignancies, such as colon, prostate, pancreas, lung and breast cancer." (PMID 31828042, 2019). "Further, we found that knockdown RAI14 inhibits the proliferation, migration and invasion of breast cancer cells by regulating cell cycle and EMT through Akt/Cyclin D1, MMP2, MMP9 and ZEB1/E-cadhrin/Vimentin pathway." (PMID 31772666, 2019). "By contrast, cells that express low levels of ZEB1/2 along with high levels of ESRP1/2 and E-cadherin were categorized into the “luminal” subtype of breast cancer with relatively good prognosis." (PMID 31682640, 2019). "Among these, the levels of ZEB1/2 in particular correlate positively with EMT phenotypes and the aggressiveness of breast cancer cells." (PMID 31682640, 2019). "ZEB1/2 are EMT transcription factors that are positively correlated with EMT phenotypes and breast cancer aggressiveness." (PMID 31682640, 2019). "In another human breast cancer cell line, MCF-7-ras cells, CAM6, E-cad, and ZEB1 mRNA expressions were also consistently induced by SDF-1 and TGF-β1 treatment." (PMID 31331982, 2019). "The NFKB pathway regulates ZEB1 or SNAI2 expression in mammary epithelial cells, and is essential for EMT and metastasis in a model of breast cancer progression." (PMID 30782064, 2019). "In the study we found that, similar to the basal-like subtype of breast cancer, OSCC cells with high levels of ZEB1/2 and low levels of E-cadherin and ESRP1/2 exhibited mesenchymal-like traits with FGFR(IIIc) isoforms." (PMID 31682640, 2019). "In breast cancer cells, decreased expression of miR-200b promoted EMT and subsequent cisplatin resistance by directly inhibiting Zeb1 and Zeb2." (PMID 31213009, 2019). "The negative correlation between hsa_circ_001783 and miR-200c-3p and positive correlation between hsa_circ_001783 and ZEB1, ZEB2, and ETS1 were further observed in the tumor tissues from breast cancer patients." (PMID 30670688, 2019). "In breast cancer, cells with high levels of ZEB1/2 and low levels of ESRP1/2 and E-cadherin are categorized into the “basal-like” subtype of breast cancer with aggressive behavior and poor prognosis." (PMID 31682640, 2019).